SIRT1 (sirtuin 1)
Diseases named in the same sentence as SIRT1 in open-access papers (continued):
Sharing a sentence is not in itself a finding about the gene and the disease.
cancer (continued). "Cancer-associated fibroblasts (CAFs) secrete lactate, which increases mitochondrial mass and activity by SIRT1-dependent PGC-1α activation in cancer cells and promotes mitochondrial transfer from CAF." (PMID 34733852, 2021). "SIRT1 inhibition in parental cancer cells with PGRMC1 overexpression blocked autophagy, but SIRT1 activation in PCC with PGRMC1 inhibition induced autophagy, which was not affected by parthenolide treatment." (PMID 34749765, 2021). "The expression and activity of SIRT1 are upregulated in tumor cells and SIRT1 expression is higher in drug-resistant cell lines and cancer patients undergoing chemotherapy." (PMID 34445574, 2021). "Sirtuin 6 (SIRT6), a member of sirtuin family (SIRT1–7), regulates a variety of cellular processes involved in aging, metabolism, and cancer." (PMID 33684691, 2021). "Resveratrol, a SIRT1 activator, is widely known for its biological functions, including anti-oxidative, anti-cancer, and longevity properties." (PMID 33668647, 2021). "On the other hand, several HBV inhibitors, for example, ONECUT1, RFX1, and SIRT1 appeared to be up-regulated in less differentiated cancer cells." (PMID 34290079, 2021). "Previously, morphine and fentanyl—nonpeptide agonists of μ-opioid receptors—have been reported to increase SIRT1 expression in the mouse brain and to inhibit NF-κB in cancer cells in a SIRT1-dependent manner, respectively." (PMID 34616852, 2021). "The regulation of FOXO1 activity by SIRT1 yields opposite biological effects in different cancer cells, emphasizing an individual role of HDACs in tumorigenesis and the response to treatment." (PMID 34769241, 2021). "Based on the upregulation of USP22 expression in cancers, the induction of necroptosis can be an effective clinical strategy to kill cancer cells with the active USP22/SIRT1 axis, which inhibits apoptosis." (PMID 33919439, 2021). "Because overexpression of SIRT1 reportedly renders cancer cells resistant to anti-cancer drugs, we examined SIRT1 levels in multidrug-resistant LS513 cells." (PMID 32151067, 2020). "The dual functions of SIRT1 in cancer progression introduce many questions regarding its function in the regulation of tumor progression, particularly tumor suppression." (PMID 32489467, 2020). "Although hypermethylation of SIRT1 has been reported in several cancer tissues, this is the first demonstration of hypermethylation of SIRT1 in OSCC." (PMID 31931863, 2020). "In fact, in cancer cells, SIRT1 inhibition augmented Ku70-acetylation, encouraging FLIP destabilization." (PMID 32630842, 2020). "This supports the assumption that the role of SIRT1 has to be examined specifically for each cancer entity and subtype." (PMID 32388637, 2020). "In many cancer types Sirt1 expression is increased and higher levels have been associated with metastasis and poor prognosis." (PMID 32426286, 2020). "Among HDACs, SIRT1, 2, and 4 were mainly located in mitochondria and cytoplasm, and they were closely related to metabolic process and oxidative stress during cancer development." (PMID 33093847, 2020). "SIRT1 (Sir2 homolog) was reported for its protective functions in several diseases in murine models, including cancers, cardiovascular disease, metabolic disorders, neurodegeneration, and aging, and its loss is implicated in aging and its associated disorders." (PMID 32526825, 2020). "Generally, SIRT1 is expressed in all cell types and largely identified as a nuclear protein, with sparse presence in the cytoplasm in certain cancer cell lines, such as A549 cells." (PMID 32489467, 2020). "As with SIRT2, there are conflicting reports of cancer suppressor and oncogenic activities of SIRT1 and 3 in various tumor types." (PMID 31973227, 2020).
cancer (continued). "Salermide has been shown to inhibit cell proliferation and induce apoptosis in cancer cell lines, acting through reactivation of pro-apoptotic genes that are repressed by SIRT1-mediated H4K16ac deacetylation." (PMID 33059738, 2020). "For potential anti-cancer therapeutic applications, aiming for a specific SIRT1 inhibition at low concentrations of EX-527 (ex." (PMID 32366137, 2020). "Among seven sirtuins, SIRT1 plays a critical role in modulating a wide range of physiological processes, including apoptosis, DNA repair, inflammatory response, metabolism, cancer, and stress." (PMID 33014276, 2020). "Recent studies have focused on the biological functions of SIRT1 in metabolic diseases, cancer, aging and cellular senescence, inflammatory signaling in response to environmental stress, and cell survival 132-135." (PMID 31956359, 2020). "Expectedly, increased levels of SIRT1 in cancer cells can confer CDDP resistance and thus represent treatment obstacle that is overcome by targeting by SIRT1 inhibitors." (PMID 32235701, 2020). "SIRT1, the best-characterized member of the sirtuin family of deacetylases, is involved in cancer, apoptosis, inflammation, and metabolism." (PMID 32158616, 2020). "It is vital to recognize that SIRT1 promotes cancer progression through modulating Akt activity 49,58." (PMID 32398958, 2020). "In support of this, reports confirmed that SIRT1 is involved in the progression of cancers by targeting the cell growth signaling pathways like Wnt-β and Akt/PI3K." (PMID 32607257, 2020). "Because SIRT1 was previously reported to act as either a tumor suppressor or promoter, depending on the cancer cell type and context of cells, this study first assessed the role of SIRT1 in the tumorigenesis of DLD1 cells." (PMID 32636443, 2020). "The role of SIRT1 in cancer cell death and progression is controversial because SIRT1 has both tumor-promoting 11 and tumor-suppressing functions." (PMID 32489467, 2020). "Considering the controversial role of SIRT1 in cancer, we evaluated the prognostic significance of SIRT1 by analyzing the correlation between SIRT1 expression and overall survival (OS) of cancer patients." (PMID 32276460, 2020). "Concomitantly, SIRT1 is associated with EMT regulation, being involved in cancer progression and metastasis." (PMID 32340156, 2020). "In cancer, SIRT1 is upregulated during EGF-mediated epithelial-to-mesenchymal transition, while in vascular smooth muscle cells, resveratrol, a SIRT1 stimulator, interferes with EGF-induced ROS production." (PMID 32106619, 2020). "LAPTM4B, RANKL OPG, YKL-40, and SIRT1 in serum showed a significant change in both cancer groups compared with control." (PMID 32102511, 2020). "SIRT1 negatively regulates the differentiation of IL-9-producing antitumor Th 9 cells in cancer and suppresses the activity of regulatory T cells." (PMID 32117717, 2020). "In PCa, elevated expression of SIRT1 has also been reported to promote cancer cells growth, invasion and neuroendocrine differentiation." (PMID 32431616, 2020). "As already mentioned Sirt1 can play very contradictory roles in different tissues and even within one cancer type." (PMID 32426286, 2020).
cancer (continued). "The relatively high expression of SIRT1 in diverse cancers and its cancer-prone effects endorse the role of SIRT1 as a tumor driver." (PMID 32276460, 2020). "Taken together, SIRT1 is integral in regulating ER-mediated transcriptional activity in different disease conditions, especially in cancers." (PMID 33330467, 2020). "Among these, upregulated genes included SNAIL2, enrolled in both EMT and collagen remodeling, SIRT1, which is an inducer of cancer stemness and chemoresistance, and CTGF, recently associated with poor prognosis in a few tumors, including OC." (PMID 32847044, 2020). "Nevertheless, SIRT1 has been shown to regulate epithelial-mesenchymal transition (EMT) in cancer cells." (PMID 32489467, 2020). "Resveratrol can inhibit the production of inflammatory factors through the activation of Sirtuin 1 (Sirt1), which is an important deacetylase involved in numerous molecular events (metabolism, cancer, embryonic development and immunotolerance)." (PMID 32764275, 2020). "Similar to Sirt1, the data related to the role of Sirt2 in cell proliferation and development of cancer are controversial." (PMID 32698385, 2020). "SIRT1, AKT1, and MTOR oscillate in both cell lines in a circadian manner and are associated with the circadian clock and cancer hallmarks." (PMID 32295075, 2020). "Some studies showed an increased cisplatin resistance with lower survival rates, while other studies described an inhibition of cancer progression by stimulation of SIRT1." (PMID 32388637, 2020). "Resveratrol positively affects Sirt1 expression to diminish mitochondrial respiration and viability of cancer cells." (PMID 32163546, 2020). "This demonstrates their high potential to further study the role of Sirt1 in cellular model systems for cancer research but also in other diseases." (PMID 32426286, 2020). "Similar reports also show that lactate uptake alters the NAD+/NADH ratio in cancer cells, which culminates in Sirt1-dependent PGC-1α activation and subsequent enhancement of mitochondrial mass and activity." (PMID 32570218, 2020). "The expression of SIRT1 was reported to predict shorter overall survival, disease-free survival, and cancer-specific survival in KIRC." (PMID 32158696, 2020). "New small molecule Sirt1 modulators are crucial for further investigation of the contradicting roles of Sirt1 in cancer." (PMID 32426286, 2020). "As determined in silico by AutoDock VINA v.1.1.2, CMH, the pro-apoptosis molecule that downregulates FLIP in cancer cells docked into a narrow hydrophobic pocket in SIRT1." (PMID 32630842, 2020). "Inhibition of SIRT1 decreases growth and viability of cancer cells while its overexpression impairs apoptosis, suggesting that SIRT1 is a critical regulator of cell proliferation and survival." (PMID 32151067, 2020). "In summary, these results provide one possible explanation for how SIRT1 dysregulation leads to genomic instability and ultimately aging or cancer progression." (PMID 31209362, 2020). "Lactate uptake stimulates SIRT1-dependent PGC-1α activation and mitochondrial mass and activity in PCa cells and cancer-associated fibroblasts." (PMID 32431616, 2020). "Taken together, these multiple substrates indicate that SIRT1 participates in the regulation of multiple physiological functions, including apoptosis, DNA repair, inflammatory response, metabolism, cancer, and stress." (PMID 33014276, 2020). "In some studies, an increased cisplatin resistance with lower survival rates was observed, while other studies showed that cancer progression was inhibited by stimulation of SIRT1." (PMID 32388637, 2020).
cancer (continued). "Our analysis of publicly available Kaplan–Meier data revealed that SIRT1 expression is negatively correlated with survival in several human cancer types." (PMID 32151067, 2020). "HDAC1, 2, 3, 4, and 7 were reported to be upregulated in PDA, whereas HDAC 2 and 3, along with SIRT1, have been reported to be involved in cancer invasion and chemo-resistance." (PMID 33244070, 2020). "Although the roles of SIRT1 in cancer are controversial, its overexpression is a feature of many solid tumors and hematopoietic malignances." (PMID 32151067, 2020). "Particularly, SIRT1 controls the activity of multiple steroid hormones via different mechanisms in cancer." (PMID 33330467, 2020). "Nonetheless, growing evidence implicates SIRT1 in cancer promotion and development of resistance to chemotherapeutical agents, including cisplatin, doxorubicin, and camptothecin." (PMID 32151067, 2020). "SIRT1 modulators in general and their roles in cancer in particular have been often reviewed, usually giving an overview of several inhibitors and activators, but limited information on each one." (PMID 32366137, 2020). "Chemotherapy on CRC induces a SIRT1/PGC1αdependent increase in OXPHOS that increases the survival of carcinoma cells." (PMID 32503256, 2020). "SIRT1 involves in cancer progression already obtaining cumulative evidence, but its exact role in carcinogenesis remains controversial." (PMID 30918653, 2019). "Our study also provided new clues for a combination of cancer therapies using SIRT1 regulators and CHK2 inhibitors." (PMID 30902968, 2019). "For example, altered SIRT1 expression in cancer cells contributes in part to cisplatin resistance by altering mitochondrial metabolism." (PMID 30710424, 2019). "In cancer cells, SIRT1 is poorly adjusted and has been featured to have a dual role as an oncogene and tumor suppressor." (PMID 31281594, 2019). "Disrupting SUMOylation by targeting either UBC9 or PIASy, the E2 and E3 small ubiquitin-like modifier (SUMO)-conjugating enzymes restored SIRT1 expression and promoted an epithelial-like phenotype of cancer cells, thereby arresting metastasis." (PMID 30761005, 2019). "An increasing number of studies report that SIRT1 has a function in metastasis and invasiveness in several cancers." (PMID 30761005, 2019). "Consistently, SIRT1 was found to be involved in the high expression of cancer stem cell markers, chemoresistance, tumorigenesis, and epithelial to mesenchymal transition (EMT) phenotype." (PMID 31572453, 2019). "Sirtuin1 (SIRT1) expression is c-Myc-dependent, and its activity is increased in a majority of cancers including GC." (PMID 31689236, 2019). "SIRT1 blockage has been proposed in the therapy of cancer, immunodeficiency virus infections, and Fragile X mental retardation syndrome and for preventing or treating parasitic disorders." (PMID 31281594, 2019). "TGF-β upregulates SIRT1, which in turn determines downregulation or degradation of E-cadherin by interacting with other TFs, promoting resistance to cell death, and cancer cell migration and invasion." (PMID 30761005, 2019). "Given the lack of evidence regarding the trans-activation effects of EGR1 and USF2 on the SIRT1 promoter in cancer, we focused on investigating the trans-activation effects of these two transcription factors." (PMID 31068761, 2019). "Here, we present evidences and discuss the recent findings on the interplay among SIRT1, oxidative stress, and DNA repair machinery and its impact on normal and cancer cells." (PMID 31261609, 2019). "A considerable body of literature has suggested the strong anti-cancer effect of Sirt1 activator Rsv, despite few reports on the cancer-promoting activity of Sirt1 activation." (PMID 31817453, 2019).
cancer (continued). "SIRT1 is a NAD dependent protein deacetylase and implicated in diverse cellular processes such as DNA damage repair, and cancer progression." (PMID 31043584, 2019). "In cancer, SIRT1 activation by a new compound increased autophagy/mitophagy thereby reducing glioblastoma growth in vitro and in vivo." (PMID 31210843, 2019). "NAD-dependent enzymes, such as SIRT1, regulate critical cellular processes necessary for cancer cell growth, including transcription, cell-cycle progression, anti-apoptosis, and DNA repair." (PMID 31430957, 2019). "Specifically, SIRT1 activation by resveratrol hampers cancer metastasis in vitro and in vivo by blocking EMT." (PMID 30761005, 2019). "In contrast, SIRT1 acts as a tumor suppressor in triple negative breast cancer cells, where it determines a block of cancer proliferation and cell growth." (PMID 30761005, 2019). "The multifaceted role of SIRT1 in carcinogenesis suggests that its function is dependent on cancer type and the state of downstream or upstream molecules that influence its oncogenicity." (PMID 31608282, 2019). "A description of the inducibility of SIRT1 and its role as the longevity factor in cytoprotection and cancer was also documented." (PMID 31281594, 2019). "Meta-regression and subgroup analysis revealed that ethnic background has influence on the role of SIRT1 expression in predicting survival and clinicopathological characteristics of cancers." (PMID 30930849, 2019). "Chemo-resistance is a phenomenon observed in tumors overexpressing SIRT1, determining hyper proliferation and survival of cancer cells." (PMID 30761005, 2019). "Previous studies have shown that SIRT1 is a key positive regulator of metastasis that induces EMT in several types of cancers." (PMID 31689236, 2019). "During CRPC progression, miR-204 targets SIRT1 gene, which is involved in cancer drug resistance by FOXO1 deacetylation." (PMID 31756185, 2019). "In recent years, the important connection of SIRT1 to cancer metastasis has been introduced, further confirming the pivotal roles of SIRT1 in cancer progression." (PMID 31068761, 2019). "SIRT1 has a pivotal role in cancer development, programmed cell death, regulation of gene expression, DNA repair, and aging mechanisms." (PMID 31287252, 2019). "Recent cancer studies have shown that SIRT1 is a reliable biomarker of cancer recurrence and implied some anticancer properties of SIRT1 agonist or resveratrol." (PMID 31207928, 2019). "SIRT1 is also involved in cancer, angiogenesis, atherosclerosis, Notch signaling regulation, diabetes, memory and learning, anxiety and neurodegenerative disorders, including AD and Huntington’s disease." (PMID 30871086, 2019). "VDR is linked with FoxO protein and also regulates the sirtuin 1 (Sirt1) class III histone deacetylase (HDAC) and protein phosphatase 1, providing a molecular basis for cancer chemopreventive actions of 1α,25(OH)2D3." (PMID 31653160, 2019). "In this study, we found that resveratrol inhibits cancer cell proliferation by activating SIRT1 to repress histone gene expression." (PMID 31598701, 2019). "A previous study showed that autophagy in cancer cells is regulated by SIRT1, which induces nuclear LC3 deacetylation and translocation to the cytoplasm." (PMID 31850196, 2019). "Here, we discuss the recent findings on the interplay among SIRT1, oxidative stress, and DNA repair machinery and its impact on normal and cancer cells." (PMID 31261609, 2019). "We have chosen to investigate four genes SIRT1, FGFR2, STAT3, and RAGE which are known to be closely associated with different types of cancer and are related to pathogenetic processes." (PMID 31781300, 2019).